MMP15 (matrix metallopeptidase 15)
Diseases named in the same sentence as MMP15 in open-access papers (continued):
Sharing a sentence is not in itself a finding about the gene and the disease.
tumor (continued). "The logistic regression model for predicting NSLN metastasis is as follows: logit (p) = −2.853 + 1.592∗ positive expression of MMP15 in cytoplasm + 3.712∗ neural invasion + 0.898∗ lymphovascular invasion + 0.641∗ tumor size + 0.904∗ the number of positive SLNs." (PMID 36035312, 2022). "MMP15 plays a role in invasion, angiogenesis, and the formation of premetastatic tumor niches." (PMID 36035312, 2022). "Tumor size, lymphovascular invasion, neural invasion, MMP15 expression in the cytoplasm, the number of positive SLNs, the number of negative SLNs, the percentage of positive SLNs, and NLR were statistically significant in univariate regression analysis (P < 0.05)." (PMID 36035312, 2022). "According to the expression pattern analysis, all the MMPs upregulated in CRC showed lower promoter methylation, except MMP11, while all the MMPs downregulated in CRC showed higher promoter methylation in tumor samples compared with normal samples, except for MMP15 and MMP27." (PMID 34830271, 2021). "For CNS HGNET-BCOR detection, three probes for SHISA8, MNX1 and MMP15 showed diagnostic usefulness regardless of tumor location." (PMID 32650833, 2020). "Since FTE data were available in this database, a comparison of cancer epithelium versus FTE was also included and, apart from the stromal derived candidates VCAN and SDC3, as well as MMP15, all other discovered biomarkers were associated with EOC and increased with tumour progression." (PMID 31336942, 2019). "Silence of TCF-4 in LLC cells significantly decreased the tumor lesions in the lungs, while additional overexpression of MMP-15 could rescued this effect." (PMID 27046058, 2016). "MT1- and MT2-MMP (MMP15) can each drive tumor cell invasion through basement membranes and the collagen type I-rich interstitial stroma, while MT3-MMP (MMP16) cannot efficiently cleave native collagen type I or confer cells with collagen-invasive ability in vitro or in vivo." (PMID 22164270, 2011). "Furthermore, the activities of MMP-14 and MMP-15 in the cells of both tumor grades were determined." (PMID 39125675, 2024). "Interestingly, MMP15 inhibits apoptosis in several tumor cell lines." (PMID 32614494, 2020). "We found that P2RX7, MMP15 and MMP16 are upregulated in neurosphere cells, indicating a potential role for these genes in tumor formation." (PMID 41400763, 2025). "After macrophage infusion, the collagen content in tumours was significantly reduced, while the expression of MMP3, MMP14 and MMP15 was increased." (PMID 31570753, 2019). "In xenograft model, TCF-4 silence-improved tumor lesions in lungs and survival time of LLC-tumor bearing mice were abolished by MMP-15 overexpression." (PMID 27046058, 2016). "Our data showed that, while MMP9 and MMP15 (MT2-MMP) expression in tumor cells was negligible in both Apcmin/+ and Apcmin/+/Stat3IEC-KO mice, MMP7 expression in tumor cells was significantly lower in Apcmin/+/Stat3IEC-KO mice." (PMID 24995503, 2014). "MT1-MMP (MMP-14) and MT2-MMP (MMP-15) both demonstrated an extremely highly significant RNA expression profile in this study, and localised to the tumour stroma." (PMID 16465195, 2006). "Expression of MMP15 and MMP16 may contribute to the neurosphere cells’ ability to establish a tumor when engrafted into mice." (PMID 41400763, 2025). "Specific MMPs, including MMP2, MMP9, MMP11, MMP14, MMP15, MMP25, and MMP28, were increased in this region, indicating their distinct roles in the tumor microenvironment and confirming the importance of understanding the effects of cysteamine on specific MMPs in GBM cancer models." (PMID 38893149, 2024). "MMP10, MMP15 and MMP9 are found to be increased in GC and to correlate with poor patient prognosis During the metastasis process, tumour cells originating from primary tumour or metastases can be found circulating in blood, either single or in clusters." (PMID 33810350, 2021).
tumor (continued). "In summary, the infusion of CAR-147 macrophages can degrade the dense collagen-based matrix that surrounds tumours, which may require the involvement of MMP3, MMP14 and MMP15." (PMID 31570753, 2019). "Downregulation of NudCD1 in tumor cells that showed a high expression of the protein resulted in a down-regulation of some oncogenic genes such as CTSL, MMP15, uPAR, VEGF, COX-2, S100A4, MUC1, MDM2 and RAC110 and an increase of the resistance to 5-fluorouracil-induced apoptosis." (PMID 29021621, 2017). "We could see that about half MMPs are highly expressed in tumor tissues as compared with normal tissues, including MMP9, MMP10, MMP11, MMP12, MMP15, MMP25, MMP26 (all, P<0.05), while some other MMPs decreased in tumor tissues, including MMP2, MMP14, MMP16, MMP24, MMP28(all, P<0.05)." (PMID 32669958, 2020).
cancer (22 papers, 2012 to 2026). A tumor composed of atypical neoplastic, often pleomorphic cells that invade other tissues. "ECM proteases generally showed a widespread negative correlation with PEBP1/STK11 co-expression across all cancer types, with the exception of MMP15 and SPG7, which displayed positive correlations in most of the cancers analyzed." (PMID 40806276, 2025). "MMP-15 demonstrated a significantly higher activity in both cancer grades, as compared to the control material." (PMID 39125675, 2024). "An increase in the cancer grade brought about a decrease in actual activity of MMP-15 by nearly 2 times." (PMID 32049862, 2020). "MMP15 has been shown to play an important role contributing to cancer progression through upregulating the capacity of migration and invasion in cancer cells." (PMID 32887509, 2020). "There were significant differences in actual activity of MMP-15 between both grades of cancer and the control tissue." (PMID 32049862, 2020). "Low-grade cancer was characterized by a higher amount of MMP-15 while its content in high-grade cancer was 4 mg/kg lower than in the control tissue." (PMID 32049862, 2020). "We then examined the influence of EGF on MMP9 transcription as well as on the transcription of additional MMPs (MMP-1, MMP-2, MMP-3, MMP-7, MMP-10, MMP-13, MMP14, MMP15) and of CD44, a cell adhesion glycoprotein implicated in EMT and cancer metastasis." (PMID 26084289, 2015). "Like MMP-14, MMP-15 has been most widely studied for its role in cancer progression and metastasis, primarily through its capacity to cleave and activate MMP-2." (PMID 22768148, 2012). "Changes in MMP15 expression levels have been described in various cancers, including BC." (PMID 36035312, 2022). "Data on the role of MMP15 in cancer deserve special attention." (PMID 36035312, 2022). "Interestingly, while the MMPs members from MMP1 to MMP14 were generally upregulated in several cancer types, the others (MMP15 to MMP28) were downregulated." (PMID 34830271, 2021). "Despite that, MMP-15 presented the highest activity at that stage of the cancer." (PMID 32049862, 2020). "The inverse changes were detected for MMP-15 in high-grade cancer." (PMID 32049862, 2020). "The MMP-15 amount was over 3 times higher than MMP-14 also in low-grade cancer tissues." (PMID 32049862, 2020). "The specific activity of MMP-15 decreased with increase of cancer histopathological grade." (PMID 32049862, 2020). "Among the 22 investigated MMPs, seven genes (MMP2, MMP3, MMP10, MMP12, MMP14, MMP15, and MMP16) were upregulated in cancer, while MMP8 was downregulated." (PMID 41728806, 2026). "Both control and cancer human kidney tissues contain MMP-14 and MMP-15 enzymes in the form of high-molecular-weight complexes." (PMID 39125675, 2024). "MT-MMPs including MMP15, are specifically expressed in the front line of invading cells and can degrade ECM in a site-specific manner during cell invasion in cancer." (PMID 34940120, 2021). "Taken together, these results indicate that cancer cell-derived exosomal miR-425-3p inhibits preadipocyte proliferation and differentiation through targeting related regulating genes such as GATA2, IGFBP4, MMP15, and CEBPA." (PMID 35941833, 2022). "Total content of MMP-14, MMP-15, and TIMP-1 in control human urinary bladder and its cancers." (PMID 32049862, 2020). "However, it appears that MMPs are important enzymes involved in local attack and metastatic PTC cancer, being reported in several studies related to different members of the MMP family, including MMP-1, MMP-2, MMP-7, MMP-9, MMP-10, MMP-13, MMP-14 and MMP-15." (PMID 30509240, 2018). "Additionally, to investigate whether LINC00482 promoted MMP15 expression by recruiting FOXA1, cancer cells were transfected with oe-NC + sh-NC, oe-LINC00482 + sh-NC, and oe-LINC00482 + sh-FOXA1." (PMID 33323547, 2020). "Other members of the MMP family (MMP15, MMP16, MMP19, and MMP27) showed no differential expression between pancreatic normal and cancer tissues." (PMID 37821678, 2023).
infection (4 papers, 2019 to 2023). The state of being infected such as from the introduction of a foreign agent such as serum, vaccine, antigenic substance or organism. "Matrix metalloproteinase MMP15 interacted with ORF7b and ORF3 and was significantly upregulated in the transcriptome after infection." (PMID 37632105, 2023).
psychiatric diseases (1 paper, 2022). "Our results showed that MMP genes such as MMP-15, MMP-16, MMP-17, MMP-24 and MMP-28 were expressed highly or moderately in brain, implying the values in investigation of more genes in association with psychiatric diseases." (PMID 35444067, 2022).
MMP15 also shares sentences with these, for which no sentence is quoted: congenital heart defects (2 papers); adenoma (1); Alagille syndrome type 1 (1); aneurysm (1); brain tumors (1); breast tumor (1); Buccal Mucosa Squamous Cell Carcinoma (1); cerebral edema (1); Cerebral ischemia (1); cholestasis (1); Cirrhosis (1); connective tissue disorder (1); endometriosis (1); endothelial dysfunction (1); fibrosarcoma (1); glioblastoma (1); glottis squamous cell carcinoma (1); interstitial lung disease (1); invasive carcinoma (1); Lip Squamous Cell Carcinoma (1); liver cancer (1); Lymph Node Metastasis (1); maxillary sinus squamous cell carcinoma (1); Mouth Squamous Cell Carcinoma (1); Oropharyngeal Squamous Cell Carcinoma (1); ovarian endometriosis (1); rheumatic diseases (1); Sepsis (1); stomach tumor (1); Supraglottic Squamous Cell Carcinoma (1).
A further 3 diseases each share a sentence with MMP15 in 1 paper.